SLC7A14 (solute carrier family 7 member 14)
Description:
Imports 4-aminobutanoate (GABA) into lysosomes. May act as a GABA sensor that regulates mTORC2-dependent INS signaling and gluconeogenesis. The transport mechanism and substrate selectivity remain to be elucidated.
Synonyms: KIAA1613; PPP1R142
Tractability: Antibody: its Gene Ontology location is reachable by antibodies, with high confidence; UniProt predicts a signal peptide or a membrane-spanning region. PROTAC: its protein half-life has been measured.
Gene: Protein-coding gene on chromosome 3 (170,459,548 to 170,586,075, reverse strand). Ensembl gene ENSG00000013293.
Subcellular location: Lysosome membrane
Subcellular location (Human Protein Atlas): Cytosol; Vesicles; Nucleoplasm; Plasma membrane
Gene Ontology:
Molecular function: protein binding; gamma-aminobutyric acid transmembrane transporter activity; L-lysine transmembrane transporter activity; transmembrane transporter activity
Biological process: amino acid transport; gamma-aminobutyric acid import; L-lysine transmembrane transport; transmembrane transport
Cellular component: lysosomal membrane; plasma membrane; membrane
Genetic constraint (gnomAD): Loss-of-function variants: 37 observed, 62.54 expected, observed/expected ratio (o/e) 0.59, 90% interval 0.45 to 0.78. The upper end of that interval is the gene's LOEUF score, 0.78, which puts it in group 3 of 6, group 1 being the genes least tolerant of losing a copy. Missense variants: 886 observed, 1,036.1 expected, observed/expected ratio (o/e) 0.86, 90% interval 0.81 to 0.9. Synonymous variants: 399 observed, 416.31 expected, observed/expected ratio (o/e) 0.96, 90% interval 0.88 to 1.04.
Homologues: Orthologues: chimpanzee SLC7A14 (99% identical), macaque SLC7A14 (99% identical), rabbit SLC7A14 (97% identical), guinea pig SLC7A14 (97% identical), mouse Slc7a14 (97% identical), pig SLC7A14 (96% identical), rat Slc7a14 (96% identical), tropical clawed frog slc7a14 (84% identical), zebrafish slc7a14a (78% identical), zebrafish slc7a14b (69% identical), Drosophila melanogaster CG12531 (42% identical), Caenorhabditis elegans F23F1.6 (27% identical), and 3 more. Paralogues in human: SLC7A1 (36% identical), SLC7A3 (36% identical), SLC7A2 (36% identical), SLC7A4 (32% identical), SLC7A8 (15% identical), SLC7A11 (14% identical), SLC7A6 (14% identical), SLC7A5 (14% identical), SLC7A10 (13% identical), SLC7A13 (13% identical), SLC7A9 (13% identical), SLC7A7 (13% identical).
Diseases named in the same sentence as SLC7A14 in open-access papers:
SLC7A14 is named in the same sentence as 15 diseases in open-access papers, as found by Europe PMC text mining. Sharing a sentence is not in itself a finding about the gene and the disease. The quoted sentences say what the papers report.
retinitis pigmentosa (3 papers, 2019 to 2021). Retinitis pigmentosa (RP) is an inherited retinal dystrophy leading to progressive loss of the photoreceptors and retinal pigment epithelium and resulting in blindness usually after several decades. "Patient #4 with mildly severe ASD was identified with a variant in SLC7A14, an amino acid transporter highly expressed in the CNS lysosome and implicated in retinitis pigmentosa." (PMID 35011571, 2021). "Previous study has identified SLC7A14 as a new causative gene of retinitis pigmentosa (RP)." (PMID 31921845, 2019).
mesothelioma (2 papers, 2013 to 2015). A usually malignant and aggressive neoplasm of the mesothelium which is often associated with exposure to asbestos. "Most of these SNPs were located in regions reported to harbor aberrant alterations in mesothelioma (SLC7A14, THRB, CEBP350, ADAMTS2, ETV1, PVT1 and MMP14 genes), causing at most a 2–3-fold increase in MPM risk." (PMID 23626673, 2013).
auditory neuropathy (1 paper, 2024). A hearing disorder characterized by impaired transmission of signals through the auditory nerve, resulting in mild to severe hearing loss and poor speech perception. "For example, the lysosomal SLC transporter encoded by the orthologs Slc7a14 and slc7a14b is highly expressed IHCs and zHCs, respectively, and loss of function causes progressive auditory neuropathy and retinopathy." (PMID 39484049, 2024).
autosomal recessive retinitis pigmentosa (1 paper, 2021). Autosomal recessive retinitis pigmentosa (RP) is an autosomally recessive inherited retinal dystrophy leading to progressive loss of the photoreceptors and retinal pigment epithelium and resulting in blindness usually after several decades. "In vertebrates, Slc7a14 codes for a glycosylated, cationic amino acid transporter protein that has recently been found to underlie the autosomal recessive retinitis pigmentosa." (PMID 33816460, 2021).
breast carcinoma (1 paper, 2025). "In our comprehensive literature search through PubMed, we found eight amino acid transporters from SLC7A1 to SLC7A14 have not been studied in breast cancer." (PMID 38204267, 2025).
hearing loss (1 paper, 2022). "Slc7a14 is expressed in IHCs, and loss of function can cause syndromic hearing loss." (PMID 35417713, 2022).
infective endocarditis (1 paper, 2022). Infective endocarditis (IE) is an infection of the inner lining of the heart chambers (endocardium) and valves. "Ex vivo analysis of aortic valve tissues showed higher expression levels of SLC7A14 mRNA for people that were protected against acquiring infective endocarditis." (PMID 36636720, 2022). "Patients with SNPs in SLC7A14 (Solute Carrier Family 7, Membere 14; possibly a cationic amino acid transporter) suggested protection against acquiring infective endocarditis." (PMID 36636720, 2022).
Insulin resistance (1 paper, 2025). Increased resistance towards insulin, that is, diminished effectiveness of insulin in reducing blood glucose levels. "Recently, it has been reported that elevated hepatic SLC7A14 induces insulin resistance, working as a transporter for importing GABA to lysosomes." (PMID 39996055, 2025). "Thus, the increased lysosomal GABA mediates SLC7A14-induced insulin resistance.mTORC2 is involved in lysosomal GABA accumulation-induced insulin resistance." (PMID 39996055, 2025).
microphthalmia (1 paper, 2019). Congenital or developmental anomaly in which the eyeballs are abnormally small. "Knockdown of slc7a14 led to dose-dependent microphthalmia that was reversed by overexpression." (PMID 31921845, 2019).
Obesity (1 paper, 2025). Accumulation of substantial excess body fat. "For example, in hypothalamus of aged mice, Solute carrier family 7 member 14 (SLC7A14) expression in decreased, and overexpression of SLC7A14 in hypothalamic POMC neurons alleviated impaired lipolysis in white adipose tissue of aged mice, thereby alleviating aged-dependent obesity." (PMID 41037185, 2025).
SLC7A14 also shares sentences with these, for which no sentence is quoted: endocarditis (1 paper); macular degeneration (1); myopia (1); ovarian carcinoma (1); retinopathy (1).